Y_RNA (Y RNA )
Gene: Miscellaneous RNA gene on chromosome 12 (27,752,874 to 27,752,986, forward strand). Ensembl gene ENSG00000252585.
Homologues: Orthologues: chimpanzee Y_RNA (93% identical), macaque Y_RNA (86% identical). Paralogues in human: Y_RNA (81% identical), Y_RNA (80% identical), Y_RNA (79% identical), Y_RNA (78% identical), RNY1P5 (77% identical), Y_RNA (77% identical), Y_RNA (76% identical), RNY1P6 (75% identical), Y_RNA (75% identical), Y_RNA (74% identical), RNY1P1 (73% identical), RNY1P11 (73% identical), and 91 more.